TNF (tumor necrosis factor)
Diseases named in the same sentence as TNF in open-access papers (continued):
Sharing a sentence is not in itself a finding about the gene and the disease.
psoriasis (continued). "IL-6 is upregulated in psoriasis and is crucial to inflammatory crosstalk and pathways, acting synergistically with IL-1 and TNF-α." (PMID 38666958, 2024). "Inhibiting TNF has shown remarkable therapeutic benefits in patients with psoriasis, psoriatic arthritis, Crohn’s disease, ulcerative colitis, ankylosing spondylitis, juvenile arthritis and many other less prevalent diseases." (PMID 38191855, 2024). "Inflammatory cytokines such as TNF-α promote inflammation that leads to excessive skin cell proliferation in psoriasis; it also supports tumor growth and the inflammatory environment necessary for cancer progression." (PMID 39513840, 2024). "TNF-α and IL-6 are related to the pathophysiology of psoriasis and serve as powerful therapeutic target." (PMID 38550599, 2024). "Nanoparticles that are bound to anti-TNF-α antibodies or contain IL-17 inhibitors have shown improved effectiveness in treating psoriasis in animal models." (PMID 39188726, 2024). "In the acute phase of classical psoriasis, interferon-α from plasmacytoid dendritic cells activate conventional dendritic cells responsible for the production of TNF-α and IL-23." (PMID 39781163, 2024). "It was critical for the initiation, development and severity of psoriasis, as well as the transition to PsA, and thus TNF-α inhibitors were used in the clinical treatment of PsA." (PMID 39335643, 2024). "Its mechanism of action, by inhibiting TNF-α, prevents the activation of T cells and the release of proinflammatory cytokines and chemokines, having a rapid effect on chronic inflammation in psoriasis." (PMID 39767248, 2024). "They reduce C-reactive protein levels and inhibit tumor necrosis factor-alpha and interleukin-1 and -6, which have an important role in the pathogenesis of psoriasis." (PMID 39120229, 2024). "SAR441566 (Sanofi) is a small molecule inhibitor of the TNF cytokine in early phase development for psoriasis." (PMID 38258121, 2024). "As a representative inflammatory skin disease occupied by large surface involvement, the occurrence and development of psoriasis is reported to be related to the disorder of many inflammation markers, such as IL-17A, IL-23, and TNF-α." (PMID 38893287, 2024). "TNF-α is a key inflammatory cytokine that is highly expressed in psoriatic lesions and plays a pivotal role in psoriasis pathogenesis." (PMID 38892253, 2024). "TNF-α is the key mediator at the onset of the common form of psoriasis, being also capable of perpetuating the disease in time." (PMID 39057098, 2024). "TNF-like weak inducer of apoptosis (encoded by TNFSF12) has also been reported to synergize with TNF to upregulate signature genes in psoriasis, where dual antagonism of these two cytokines results in a lower number of proliferating keratinocytes." (PMID 39297883, 2024). "Studies have shown that cytokines such as IL-23, IL-17, IL-1, and TNF-α play important roles in psoriasis pathogenesis and that molecules that target such substances exhibit significant results in the treatment of plaque and pustular psoriasis." (PMID 39199158, 2024). "Results indicated that IDG and DXM significantly inhibited the expression of IL-6, IL-17A, MCP-1, and TNF-α in psoriasis-like lesions, with all findings reaching statistical significance, while the effect on IL-13 was not statistically significant." (PMID 39465158, 2024). "The skin lesions in patients with psoriasis induced by TNF-α inhibitors are characterized by IFN-α overexpression compared with those in patients with psoriasis vulgaris." (PMID 38495878, 2024). "Selective blockade of IL-23p19 with guselkumab was superior to blockade of TNF-α with adalimumab (ADA) in treating moderate-to-severe psoriasis." (PMID 39114670, 2024). "Patients with psoriasis undergoing biologics treatments were enrolled in this study, and were categorized based on the type of biologics administered, TNF, interleukin (IL)-17, or IL-23 inhibitors." (PMID 38987260, 2024).
psoriasis (continued). "Th17, fundamental in the immunopathogenesis of psoriasis, produce cytokines that stimulate the proliferation of keratinocytes, such as IL-17, or of a pro-inflammatory nature, such as TNFα." (PMID 38601151, 2024). "IL-9, a pro-inflammatory cytokine, enhances the production of IL-17, IL-13, IFN-γ, and TNF-α in psoriasis, contributing to the inflammatory response." (PMID 38792999, 2024). "The researchers suggested that systematically infused hUC-MSCs exert a therapeutic effect on psoriasis through the TNF-α/NF-κB/MMP13 pathway." (PMID 39595528, 2024). "Key active compounds, such as piperine, piperlongumine, α-humulene, schizandrin A, schizandrin II, and torilin, were prioritized for their ability to target psoriasis-associated proteins, including STAT3, TNF, IL-6, and NF-κB." (PMID 39590306, 2024). "Therapies targeting both TNF-α and IL-17 or IL-23 have been specifically developed to address the complex immune dysregulation seen in psoriasis." (PMID 39063004, 2024). "The key role of the tumor necrosis factor-alpha (TNF-α)/interleukin-23 (IL-23)/interleukin-17 (IL-17) axis in psoriasis, especially plaque psoriasis, is well-documented." (PMID 38813379, 2024). "A notable feature of these changes is the new onset or exacerbation of psoriasis during anti-TNFα or anti-IL-6 therapy, with such reactions being more prevalent in women and typically presenting as palmoplantar impetigo." (PMID 39684717, 2024). "Among SpA-related extra-musculoskeletal manifestations, they were more likely to suffer from psoriasis and inflammatory bowel disease, but they were to a lesser extent treated with DMARDs, in particular TNF inhibitors." (PMID 38598034, 2024). "Although TNF is a key mediator of the host defence response, it also plays a pathological role in autoimmune diseases, with elevated TNF levels observed in arthritis, psoriasis and IBD." (PMID 39850904, 2024). "For patients with moderate-to-severe psoriasis, systemic biologic agents targeting tumor necrosis factor-alpha (TNF-alpha) and interleukin 12/23 (IL-12/23) were the first therapies to transform disease management." (PMID 39857589, 2024). "This study aimed to measure the associations between inflammatory biomarkers, IL-17A, TNF-α, hs-CRP, and atherosclerosis in patients with psoriasis." (PMID 39104857, 2024). "Nonetheless, additional research is required to elucidate the influence of TNF-α on NO production within the context of MTX-induced nephrotoxicity in psoriasis." (PMID 39526234, 2024). "Previous findings have shown an increased expression of tumor necrosis factor (TNF)-α, nuclear factor kappa B, IL-6, and IL-8 in psoriasis-affected nails." (PMID 39459016, 2024). "By inhibiting TNF, it is possible to block inflammatory pathways and effectively relieve psoriasis symptoms." (PMID 39590306, 2024). "The explicit role of TNF in the pathogenesis of psoriasis has been established by its significance as a blocker treatment for the disease." (PMID 38674328, 2024). "Biologics represent a critical advancement in treating psoriasis, encompassing tumor necrosis factor-α inhibitors, IL-17 inhibitors, IL-23 inhibitors, and IL-12/23 inhibitors." (PMID 39684717, 2024). "Tumor necrosis factor α (TNFα) plays a significant role in various inflammatory skin conditions, including psoriasis." (PMID 38792999, 2024). "Certolizumab pegol is a pegylated anti-TNF F(ab’) fragment of a humanized mAb that has been launched for CD, psoriasis, and RA treatment." (PMID 39297883, 2024). "In recent years, the introduction of biologic therapies targeting specific disease pathways, such as tumor necrosis factor α (TNF-α) and IL-17 and IL-23 inhibitors, represents a significant progress in the treatment of moderate-to-severe psoriasis." (PMID 39124750, 2024). "For instance, psoriasis exhibits all five expanding patterns and increased levels of pro-inflammatory mediator (TNF-α), which is consistent with our theoretical results." (PMID 38236792, 2024).
psoriasis (continued). "The immune patterns of the three patients were compared with those detectable in classical, chronic plaque-type psoriasis or paradoxical psoriasis induced by anti-TNF-α therapy, mostly sustained by adaptive and innate immunity processes, respectively." (PMID 38495872, 2024). "As an enzyme inhibitor, Apremilast inhibits phosphodiesterase 4 (PDE4), which in turn decreases the expression of pro-inflammatory cytokines TNF-α and IL-23, shows therapeutic efficacy in psoriasis, psoriatic arthropathies, and Behçet’s syndrome." (PMID 38444844, 2024). "We characterized blood and tissue PD responses in individuals with psoriasis treated with IL-23p19 blockade using guselkumab versus TNF-α blockade using ADA over the course of 48 weeks." (PMID 39114670, 2024). "In this context, an increased transcript level of pro-inflammatory factors such as IL-6 is the essential hallmark of the disease in addition to further described cytokines important in psoriasis pathogenesis such as TNF-alpha, IL-22 and IL-17." (PMID 37707681, 2024). "A recent Swedish registry study showed the presence of extra-musculoskeletal manifestations, particularly uveitis and psoriasis, in axSpA negatively impacted upon TNF inhibitor survival." (PMID 38435412, 2024). "TNF antagonistic biologics have been in development for three decades and are approved for inflammatory conditions, including CD, psoriasis, RA, and UC." (PMID 39297883, 2024). "The inhibition of TNFα can induce various responses in patients, including the induction of paradoxical psoriasis, a type of psoriasis that is Th cell-independent and driven by Type-I IFN signaling." (PMID 38303723, 2024). "This case report presents an instance of Tumor Necrosis Factor-α Inhibitor-induced psoriasis (TNFiIP), also known as paradoxical psoriasis, in a 30-year-old male with fistulizing Crohn’s disease." (PMID 39927272, 2024). "In psoriasis, T-cells are overly activated, leading to increased levels of inflammatory cytokines such as tumor necrosis factor-α (TNF-α), interleukin (IL)-17A/C/F, IL-22, and interferon-γ (IFN-γ)." (PMID 38731900, 2024). "The recent supposed pathogenesis of psoriasis involves various cytokines like interleukin (IL)-1, IL-8, tumor necrosis factor (TNF-alpha), interferon (IFN-gamma), transforming growth factor (TGF-alpha), and others." (PMID 39552957, 2024). "Adalimumab, was the most frequently used tumor necrosis factor alpha (TNF-α) inhibitor amongst psoriasis patients with Crohn’s disease (34.7%), uveitis (22.3%), systemic lupus erythematosus (14.4%), autoimmune thyroiditis (11.7%), and lichen sclerosus (10%)." (PMID 38957840, 2024). "This is evident as osteoclast precursors formation is promoted by the pro-inflammatory factors of psoriasis, such as interleukin-17 (IL-17) and tumor necrosis factor alpha (TNF-α)." (PMID 39399309, 2024). "The target proteins of these active compounds, including IL1B, TNF, STAT3, IL6, NOS2, and NFKBIA, were found to be directly associated with psoriasis-related disease proteins." (PMID 39590306, 2024). "A prominent development by Samir Mitragotri’s team involves the creation of NFKBIZ siRNA, which effectively inhibits the expression of aberrant genes and downregulates psoriasis-related signals, including TNF-α and IL-17A." (PMID 39684717, 2024). "The first biologic treatments for psoriasis that are still in use nowadays, TNF-α inhibitors, were introduced more than 20 years ago." (PMID 38731900, 2024). "In this study, the time to occurrence of the first NMSC after the initiation of TNFα inhibitors was shorter and the rate of NMSCs was higher in psoriasis patients compared to RA patients." (PMID 38730981, 2024). "We also found that IL-6 and TNF-α are aberrantly expressed in psoriasis reactions induced by anti-PD-1, at levels comparable with chronic psoriasis." (PMID 38495872, 2024).
psoriasis (continued). "Macrophages residing within psoriasis lesions represent a critical source of TNF-α and play a pivotal role in the pathogenesis of the disease." (PMID 39684717, 2024). "In a clinical trial, endothelial function—measured by flow-mediated dilation (FMD)—exhibited improvement in patients with psoriasis following treatment with inhibitors targeting tumor necrosis factor-alpha (TNF-α) and Interleukin (IL)-17A." (PMID 39519167, 2024). "TNF‐α, IL‐1β, IL‐23, IL‐17, IL‐22, Cox2, and iNOS are all inflammatory cytokines involved in the pathogenesis of psoriasis, and CXCL1, CXCL8, and CCL20 are antimicrobial peptides and chemokines produced by keratinocytes." (PMID 38967379, 2024). "Classes of biologic treatments currently used in the treatment of psoriasis are TNF-α inhibitors, anti-IL-12/23, anti-IL-23, and anti-IL17 antibodies." (PMID 38731900, 2024). "Psoriasis is largely driven by T helper (TH) 1 (TH1) and TH17 cells with the involvement of IL-17A, TNF-α and IL-22, whereas AD is associated with infiltration of TH2 cells in particular." (PMID 38251799, 2024). "TNFα inhibitors, IL-17 inhibitors, and IL-23 inhibitors have been introduced to treat psoriasis, and IL23 inhibitors (IL-1 and IL-36 inhibitors in clinical trials) to treat PPP." (PMID 38500951, 2024). "The correlation between IL-6 and TNF-α, and the development of psoriasis has been widely recognized." (PMID 39777115, 2024). "The brilaroxazine Lipogel TNF‐α levels appear lower in magnitude than the Psoriasis group (p = 0.435) and similar to the Sham non‐induced controls (NS)." (PMID 38363081, 2024). "Our results show upregulation of miR-205 and higher TNF-α levels in patients with psoriasis than in controls." (PMID 39044928, 2024). "The TNF signaling pathway is markedly upregulated in imiquimod-induced mouse psoriasis lesions, and TNF-α, a crucial target of this pathway, mediates inflammatory responses and is an inflammatory cytokine linked to PsD pathogenesis." (PMID 39072329, 2024). "In psoriasis, IL-17 is produced by Th17 cells stimulated by IL-23, while TNF-α is involved at many points in its immune pathways, e.g. stimulating the release of IL-23 by dendritic cells." (PMID 39478628, 2024). "Early studies, identified TNF-α is a key trigger of the innate inflammatory pathway in psoriasis, and as the understanding of the disease has advanced, the IL-23/IL-17A axis at the core of psoriasis pathogenesis." (PMID 38917217, 2024). "From an immunological viewpoint however, there are common pathways for psoriasis and sarcoidosis, like the TNF-α axis, and for psoriasis and eczema, like interleukin 17-E (IL-17E)." (PMID 39478628, 2024). "The increased expression of miR-155 in atherosclerosis, psoriasis, and RA and its correlation with TNF-α and IL-1β make it an interesting target for future research and a potential therapeutic target." (PMID 38927529, 2024). "The current guidelines by the American Academy of Dermatology (AAD) recommend biologics and systemic treatments like methotrexate, cyclosporine, and newer biologics targeting IL-17, IL-23, and TNF-α for moderate to severe psoriasis." (PMID 39549073, 2024). "This suggests that the specific inhibition of TNF-α, which is the target of these drugs, leads to a reduction in aDCs and pDCs, thereby relieving the symptoms of psoriasis." (PMID 38596682, 2024). "Although biological therapies such as TNF inhibitors and IL-17A inhibitors are already widely used for the treatment of psoriasis and PsA over the past two decades, only very little is known about their effects on the entire immune system long-term." (PMID 38673054, 2024). "Using this model, we observed that biologic disease-modifying antirheumatic drugs were less likely to be switched compared to the majority of other psoriasis therapies, whereas TNF-α inhibitors combined with csDMARDs had a higher switching rate." (PMID 38738977, 2024).
psoriasis (continued). "Such considerations would help to tease out statistical significance, particularly related to TNF‐α level comparisons between brilaroxazine Lipogel and the Psoriasis groups, particularly with the Sham control cohort." (PMID 38363081, 2024). "In this research, we determined the expression of key mediators of IL-17, IL-23, and TNF-α which are involved in the pathogenesis of psoriasis-like inflammation by the RT-PCR technique." (PMID 38402151, 2024). "We excluded 314,146 ICSRs reporting data about patients using an anti-TNF drug for an indication other than psoriasis." (PMID 39065754, 2024). "M1 macrophages play a pro-inflammatory role by secreting inflammatory cytokines such as TNF-α and IL-6, which accelerate the exacerbation of psoriasis." (PMID 38255845, 2024). "We discuss the role of tumor necrosis factor in psoriasis while describing possible mechanisms for this paradoxical reaction." (PMID 39781163, 2024). "Research shows that genistein can lower the production of inflammatory cytokines that depend on NF-κB in keratinocytes that are activated by TNF or LPS in a model of psoriasis." (PMID 39296901, 2024). "Interactions between the neuropeptides and mast cells induces inflammation by causing mast cells to release inflammatory cytokines IL-1β and TNF-α, and it contributes to the complex pathogenesis of itch in psoriasis." (PMID 39337637, 2024). "Similar conclusions were reached by a group of researchers from Italy, who compared the effect of developing a cutaneous malignancy through phototherapy and TNF biologic treatment in patients with psoriasis." (PMID 39274426, 2024). "Luteolin was discovered to improve psoriasis-like skin lesions by inhibiting the infiltration of immune cells and reducing the expression of IL-6, IL-1β, TNF-α, IL-17A, and IL-23." (PMID 38398617, 2024). "As a result, the serum levels of TNF-α are significantly increased in psoriasis patients and positively correlated with the PASI score." (PMID 39057098, 2024). "Numerous cases have been reported of patients with psoriasis who develop MF after starting immunosuppressive therapies, such as anti-tumor necrosis factor agents." (PMID 39507477, 2024). "IFN-γ/TNF-α-treated keratinocytes of psoriasis patients strongly express SOCS3 and SOCS1, at higher levels as compared to healthy cells." (PMID 38975347, 2024). "We observed a similarity in terms of safety in pregnant patients with psoriasis among all the anti-TNF-alpha drugs analyzed." (PMID 39065754, 2024). "In recent decades, there have been significant advances in psoriasis treatments, particularly with the development of biologic agents like tumor necrosis factor (TNF) inhibitors and interleukin (IL) inhibitors." (PMID 38348339, 2024). "Research used both in vitro and in vivo models, such as imiquimod-induced psoriasis in mice and TNF-stimulated HaCaT cells, to examine the expression levels and patterns of SIRTs in psoriasis." (PMID 39456475, 2024). "Clinical studies have demonstrated that tumor necrosis factor (TNF), interleukin (IL)-23, and IL-17 play pivotal roles in the pathogenesis of psoriasis." (PMID 38312837, 2024). "The results showed that the IL-17A, IL-6, IL-23, and TNF-α levels increased significantly in IMQ-induced mice with psoriasis." (PMID 39062965, 2024). "Studies have shown the up-regulation of TNF-a in the initiation and persistence of psoriasis, an immune-mediated inflammatory and chronic skin disorder." (PMID 38951806, 2024). "For instance, anti-TNF-α therapy has been shown to reduce EPCR expression on T cells in psoriasis patients." (PMID 39184533, 2024). "The aim of this pharmacovigilance study was to analyze data on safety of anti-TNF drugs indicated for psoriasis in pregnant women." (PMID 39065754, 2024).